RNU6-744P (RNA, U6 small nuclear 744, pseudogene)
Gene: Small nuclear RNA gene on chromosome 2 (113,681,111 to 113,681,217, forward strand). Ensembl gene ENSG00000202427.
Homologues: Orthologues: chimpanzee U6 (100% identical), macaque U6 (93% identical), guinea pig U6 (81% identical), rabbit U6 (64% identical). Paralogues in human: RNU6-1175P (89% identical), RNU6-1209P (89% identical), RNU6-1287P (88% identical), RNU6-1309P (88% identical), RNU6-188P (88% identical), RNU6-242P (88% identical), RNU6-371P (88% identical), RNU6-560P (88% identical), RNU6-742P (88% identical), RNU6-83P (88% identical), RNU6-1060P (87% identical), RNU6-116P (87% identical), and 1288 more.